BMP6 (bone morphogenetic protein 6)
Diseases named in the same sentence as BMP6 in open-access papers (continued):
Sharing a sentence is not in itself a finding about the gene and the disease.
diabetes (9 papers, 2010 to 2024). "Nevertheless, this novel role of BMP6 in the pancreas, liver and the systemic glucose homeostasis suggests a unique function of BMP6 that can be utilized for the treatment of diabetes." (PMID 30539233, 2019). "Collectively, we demonstrate that BMP6 improves glycaemia in T2D mice and regulates glucose metabolism in hepatocytes representing an exciting prospect for future treatments of diabetes." (PMID 30539233, 2019). "Both BMP4 and BMP6 have been reported to exert anti-inflammatory effects in human adipocytes and in the context of renal fibrosis in diabetes, respectively." (PMID 29222456, 2017). "TGF-b can antagonize BMP-6 signaling and regulate smooth muscle cell differentiation, leading to enhanced intimal hyperplasia, as found in a mouse model of diabetes, by regulating circulating smooth muscle progenitor cells (SPCs), and TGF-β/BMP-6 expression promotes intimal hyperplasia in mice." (PMID 37373529, 2023). "Therefore, the topical application of BMP-6 is promising to reverse the healing inhibition of diabetes." (PMID 36213270, 2022). "In conclusion, downregulation of BMP-6 at 35 kDa may correlate with the impaired fracture healing in diabetes." (PMID 32448307, 2020). "We hypothesized that SPC differentiation would be increased in diabetes and focused on modulation of TGF-β/BMP-6 signaling as potential underlying mechanism." (PMID 20858224, 2010). "Further studies are required to evaluate if inhibition of SPC differentiation, e.g. by modulating the TGF-β/BMP-6 expression, may reduce intimal hyperplasia in diabetes." (PMID 20858224, 2010). "Therefore, it may indicate that the BMP-6 (35 kDa) participated in fracture healing, which was significantly inhibited by diabetes (by up to 34.01%)." (PMID 32448307, 2020). "Therefore, the finding may suggests that diabetes downregulates the BMP-6 at 35 kDa through slowing down its maturing procedure." (PMID 32448307, 2020). "It is interesting that BMP6 in particular had an antagonising effect on TGF-β-driven DD, because it has been shown that myofibroblast progenitor cells derived from patients with diabetes are deficient in BMP6 expression, and there is some evidence of a relationship between diabetes and DD." (PMID 21711521, 2011). "In vivo metabolic tests (GTT and ITT) did not indicate symptoms of diabetes or insulin resistance in BMP6−/− mice." (PMID 39063084, 2024). "Regarding glucose metabolism, BMP6−/− mice did not develop any symptoms of diabetes, at least not until 3 months of age." (PMID 39063084, 2024). "Although the potential participation of BMP-6 in bone formation was indicated in previous researches, the role of the compound in diabetes-related impairment of fracture healing has not been elucidated." (PMID 32448307, 2020). "In addition, we evaluated the effect of diabetes on TGF-β-expression in cultured SPC, as TGF-β is known to counteract BMP-6 signaling and enhance intimal hyperplasia." (PMID 20858224, 2010). "This discrepancy could be explained by a difference in the animal models used, since there are, to our knowledge, no studies considering diabetes or other glucose metabolism disturbances in BMP6−/− mice." (PMID 39063084, 2024). "Also, we were unable to reliably quantify TGF-β and BMP-6 protein levels in the cultured SPC and thus did not exclude if posttranscriptional modulation may have attenuated the effects of the presence of diabetes on TGF-β and BMP-6 gene expression." (PMID 20858224, 2010).
renal fibrosis (8 papers, 2015 to 2023). A final common manifestation of a wide variety of chronic kidney diseases characterized by glomerulosclerosis and tubulointerstitial fibrosis. "Although these studies were based on the fact that BMP6 deficiency exacerbates renal fibrosis and liver fibrosis, the results are consistent for BMP6‐mediated inhibition of fibrotic state in different organs." (PMID 37313693, 2023). "Remarkably, in vivo studies have confirmed that deficiency of the BMP6 gene can increase renal fibrosis and upregulate TGF-β1 after renal injury." (PMID 37110199, 2023). "BMP-2, -4, and -7 have been demonstrated to have anti-inflammatory activity in the stomach of mice, and BMP-6 and -7 are protective in renal fibrosis." (PMID 29849494, 2018). "Success of BMP-6 & 7 (inhibitors of EMT induced fibrotic process) in reversal of renal fibrosis in animal models is encouraging to conduct further research to identify the common switch of EMT in DE." (PMID 28273122, 2017). "In CDDP-induced rat renal fibrosis, BMP-6 expression was seen in abnormal renal epithelial cells and also in peri-tubular myofibroblasts in CDDP-induced rat renal fibrosis." (PMID 26729181, 2015). "In combination with several previous studies, our results suggest that the BMP6 gene might ultimately be involved in CKD by regulating renal fibrosis as well as IDO activity via the TGF-β signaling pathway." (PMID 37110199, 2023). "Thus, up-regulated miR-320c expression could induce down-regulation of BMP6 and aggravate renal fibrosis." (PMID 26930277, 2016). "BMP-6 and BMP-7 might emerge as a possible new therapeutic tool to improve progressive renal fibrosis." (PMID 26729181, 2015).
lymphoma (7 papers, 2005 to 2025). A malignant (clonal) proliferation of B- lymphocytes or T- lymphocytes which involves the lymph nodes, bone marrow and/or extranodal sites. "These gene expressions are germinal center B-cell (GC-B), lymphoma node, proliferation, BMP6 and MHC." (PMID 24386617, 2013). "For the cure model, four of these genes substantially describe patients’ survival times, namely GC-B (β1), lymphoma node (β2), BMP6 (β4) and MHC (β5) signature." (PMID 24386617, 2013). "For both models, only three genes i.e. lymphoma node, BMP6 and MHC signature in the ABC phenotype were highly associated with the survival times of the patients." (PMID 24386617, 2013). "Furthermore, high levels of BMP6 and BMP7, along with ACVR1, are associated with longer survival in lymphoma patients, underscoring the clinical relevance of this study." (PMID 38229201, 2024). "In addition, BMP7, which is methylated in 23% of the analyzed patients, as well as BMP6, which previously has been reported to be frequently methylated in lymphoma, are members of the TGF-β superfamily of cytokines." (PMID 25226156, 2014). "Shut‐down of the BMP6 gene by promoter methylation was observed in malignant lymphomas." (PMID 24963031, 2014). "The relationship between BMP-7 and survival of lymphoma patients has not been studied, but expression of BMP6 has previously been associated with prognosis in patients with hematological malignancies." (PMID 23049692, 2012). "Expression of BMP-6 has been detected in some lymphoma cell lines, but the expression of BMPs in adult lymphoid tissue is largely unknown." (PMID 23049692, 2012). "Additionally, our findings that BMP-6 activates intracellular signalling pathways in human B cells might be of potential pathophysiological significance in lymphoma and inflammation." (PMID 15877825, 2005). "We checked the expression of known BMP ligands for ACVR1 and found that only BMP6 and BMP7 are expressed at high levels in lymphoma samples in CCLE and TCGA." (PMID 38229201, 2024). "BMP6 and BMP7 are upregulated by PRC2 inhibition or depletion in lymphoma cells and we purchased and applied them individually." (PMID 38229201, 2024). "Elevated BMP6/7 and ACVR1 correlate with extended survival in lymphoma patients, underscoring its clinical relevance and potential usage as biomarker." (PMID 38229201, 2024). "Studies in lymphoma cell lines of different subtypes showed that seven out of ten expressed BMP7, whereas three out of ten had detectable BMP6 levels." (PMID 23049692, 2012). "The genes BMP6, BMP7 and ACVR1 are directly repressed by PRC2 in lymphoma cells." (PMID 38229201, 2024).
hemochromatosis (6 papers, 2012 to 2025). A disorder of iron metabolism characterized by a triad of HEMOSIDEROSIS; LIVER CIRRHOSIS; and DIABETES MELLITUS. "More recently, mutations in the BMP6 gene affecting the processing of the precursor BMP6 pro-peptide to mature BMP6, were linked to an autosomal dominant form of mild hemochromatosis due to hepcidin deficiency." (PMID 30420953, 2018). "In a mouse model of hemochromatosis, mutations in a BMP6 co-receptor (i.e., HJV) were found to result in an accumulation of iron in mouse retinal tissues and upregulation of BMP6 along with upregulation of VEGF that resulted in subsequent abnormal vascularization of the retina." (PMID 30255811, 2018). "The importance of Bmp6 and hemojuvelin in hepcidin expression is evident from the fact that disruption of mouse Bmp6 or Hfe2 genes results in severe hemochromatosis, which is in terms of tissue iron overload similar to hemochromatosis caused by disruption of the hepcidin gene itself." (PMID 22629388, 2012). "However, LSECs in hemochromatosis Hjv KO mice express high Bmp6 levels despite being iron-deficient due to FPN1 stabilization by low hepatocyte hepcidin production, suggesting that other mechanisms are involved in Bmp6 upregulation." (PMID 36835406, 2023). "However, this block can be overcome by activating BMP6-hepcidin axis, because BMP6 alone is able to ameliorate hemochromatosis in the absence of BMP5." (PMID 39965404, 2025).
liver fibrosis (6 papers, 2017 to 2025). "Additionally, loss of BMP6 was found to exacerbate liver fibrosis in a mouse model of non-alcoholic fatty liver disease, while recombinant BMP6 inhibited HSC activation and reduced profibrogenic and inflammatory gene expression in activated HSC in vitro." (PMID 37798809, 2023). "BMP6 signalling has the ability to limit the development of liver fibrosis in mice and humans and reverse the fibrosis of HK-2 cells induced by TGF-β." (PMID 39915830, 2025). "Our work identifies BMP6 as a key ligand in liver fibrosis in humans." (PMID 38768139, 2024). "Interestingly, BMP6 has been previously identified as a target in murine models where the enhancement of its expression inhibits hepatic fibrosis in liver disease." (PMID 38768139, 2024). "Both BMP-2 and BMP-6 can similarly attenuate kidney fibrosis in rodent models of kidney disease, and BMP-6 expression is increased in humans and mice suffering non-alcoholic fatty liver disease (NAFLD) and is protective for hepatic fibrosis." (PMID 28769795, 2017). "Notably, an enhanced hepatic BMP6 expression was only detected in diet-induced NAFLD mice but not in both BDL and CCl4 models of liver fibrosis." (PMID 37106416, 2023).
lung carcinoma (6 papers, 2005 to 2021). "BMP6 was a tumor suppressor of lung cancer, and the loss of BMP6 expression was tightly associated with the poor prognosis of the NSCLC patients." (PMID 34036102, 2021). "In non-small cell lung cancer however, reduced BMP-6 expression was associated with reduced overall survival and BMP-6 inhibited the proliferation of lung cancer cells." (PMID 33842333, 2021). "Furthermore, this coinactivation of BMP3b and BMP6 is significantly associated with mutation of k-ras codon 12 in lung cancer (P=0.003); those with a k-ras mutation were six times more likely to have concurrent methylation of these BMP loci." (PMID 16175182, 2005). "Different from BMP2, BMP6 has been reported to be a tumour suppressor in lung cancer, which may be epigenetically silenced in lung cancer." (PMID 32750747, 2020). "This statistically significant association between concurrent methylation of BMP3b and BMP6 (P=0.009) indicates that the epigenetic silencing of these genes does not occur independently in lung cancer." (PMID 16175182, 2005). "Our data, showing that epigenetic inactivation of BMP3b (at a frequency similar to that previously reported) and BMP6 tend to occur together in lung cancer, suggests that in NSCLC multiple BMPs may need to be silenced in order to abrogate their antigrowth signalling." (PMID 16175182, 2005).
Sjögren’s syndrome (6 papers, 2016 to 2024). "BMP6 is a central cytokine in the induction of Sjögren’s syndrome–associated (SS-associated) secretory hypofunction." (PMID 35113815, 2022). "Prior studies that have introduced the expression of viral proteins, including HCV and HTLV-1 proteins, or endogenous proteins associated with pSS, including bone morphogenic protein 6 (BMP-6), have shown incomplete primary Sjögren's syndrome-like phenotypes." (PMID 27294212, 2016).
Alzheimer disease (5 papers, 2016 to 2025). A progressive, neurodegenerative disease characterized by loss of function and death of nerve cells in several areas of the brain leading to loss of cognitive function such as memory and language. "Bone morphogenetic protein 6 (BMP6) has been implicated in the pathogenesis of Alzheimer's disease (AD), and its levels have been reported to be associated with cognitive performance." (PMID 40734820, 2025). "Interestingly, BMP6 has been recently associated with Alzheimer disease and reduced neurogenesis both in human patients and in transgenic mice." (PMID 27545843, 2016). "Moreover, BMP6 displayed sex-dependent expression differences between healthy and Alzheimer’s disease conditions in public scRNA-seq datasets (ADRCSC)." (PMID 41382294, 2025).
Insulin resistance (5 papers, 2017 to 2024). Increased resistance towards insulin, that is, diminished effectiveness of insulin in reducing blood glucose levels. "Since increased plasma levels of triglyceride and cholesterol are frequently associated with insulin resistance, we wanted to determine their levels following 6 days of BMP6 treatment." (PMID 30539233, 2019). "Collectively, these findings suggest the BMP2 and BMP6 pathway(s) as promising new drug targets to treat insulin resistance." (PMID 29222456, 2017). "BMP6 improves hyperglycemia and insulin resistance, and the higher expression of glucose transporter 4 as well as an increase in brown fat mass may have a role herein." (PMID 39200147, 2024). "BMP6 improves hyperglycemia and insulin resistance, and this may ameliorate the severity of metabolic liver disease." (PMID 39200147, 2024).
osteoporosis (5 papers, 2017 to 2025). A condition of reduced bone mass, with decreased cortical thickness and a decrease in the number and size of the trabeculae of cancellous bone (but normal chemical composition), resulting in increased fracture incidence. "The gene expression profiling of markers involved in the pathways of osteogenesis and osteoporosis revealed a significant upregulation of BMP6, a marker specifically associated with oestrogen and with a strong anabolic activity in osteoporotic bone, around the magnesium-doped surfaces." (PMID 28349251, 2017). "In the progression of osteoporosis, induction of BMP-6 expression can concomitantly improve osteoblast maturation and bone formation." (PMID 32580515, 2020). "BMP6 is a protein that plays key roles in the formation of bone and in the regulation of osteoporosis, bone cancer, and fracture healing." (PMID 32059748, 2020). "This relationship between BMP6 and oestrogens prompted researchers to test BMP6 as an anabolic agent to promote bone matrix formation in osteoporosis." (PMID 28349251, 2017). "Of interest is that the BMP6 has a functional relationship with 17β-estradiol (E2), the female gonadal steroid responsible for osteoporosis in postmenopausal women." (PMID 28349251, 2017). "Future research could focus on developing specific GPR30 agonists or multi-target drugs that jointly regulate the BMP-6/HEP/FPN pathway for the treatment of osteoporosis and other ferroptosis-related diseases." (PMID 40076648, 2025). "This study is the first to reveal the critical role of GPR30 in regulating iron death in BMSCs through the BMP-6/HEP/FPN signaling pathway, which may have potential protective effects against osteoporosis (OP)." (PMID 40076648, 2025).
osteosarcoma (5 papers, 2007 to 2023). A usually aggressive malignant bone-forming mesenchymal neoplasm, predominantly affecting adolescents and young adults. "Here, we report that RNF4 via BMP6 and RGMb is required for tumor cell survival and tumorigenicity of osteosarcoma and RTK inhibitor-resistant melanoma cells (A375R)." (PMID 36153321, 2022). "We, therefore, investigated what roles RNF4, BMP6, and RGMb play in osteosarcoma and melanoma cancer cells." (PMID 36153321, 2022). "In contrast, when tumors from an osteosarcoma clone with low expression of BMP-6 mRNA (CMT 353 B, clone 6) were analysed, only weak, diffuse BMP-6 staining was observed." (PMID 19771160, 2009). "When assessing the levels of BMP-6 protein in the various tumors we found that tumors derived from high BMP-6-expressing spindle cell and osteosarcoma clones, as expected, were strongly positive for BMP-6 protein." (PMID 19771160, 2009). "Importantly, patient-derived sarcomas such as osteosarcoma, Ewing sarcoma, liposarcomas, and leiomyosarcomas exhibit high levels of RNF4 and BMP6, which are associated with reduced patient survival." (PMID 36153321, 2022). "Moreover, we found that the RNF4-RGMb-BMP6 axis is essential for survival and tumorigenicity of osteosarcoma and therapy-resistant melanoma cells." (PMID 36153321, 2022). "However, it was shown that high expression of BMP-6 is found in osteosarcoma tissues with chondroid differentiation." (PMID 36139691, 2022). "Moreover, all of the clones, except CMT-U353B clone 6, expressed high levels of BMP-6 while BMP-2 expression varied among the osteosarcoma clones." (PMID 19771160, 2009). "Also tumors formed from a high BMP-6-expressing osteosarcoma clone (CMT-U353 B, clone 2) showed strong staining for BMP-6, with particularly strong staining at the edge of the tumor." (PMID 19771160, 2009). "Since RGMb is present on the surface of hBMSCs and BMP6 is a secreted factor, we used naturalizing antibodies to each of these factors and tested for inhibition of proliferation and formation of tumor spheres of osteosarcoma U-2-OS cells and melanoma A375R cells." (PMID 36153321, 2022). "Taken together, our data suggest that RNF4 and its downstream target genes, BMP6 and RGMb, are essential for the survival of osteosarcoma and RTKi-resistant melanoma cells and that RNF4 and BMP6 may serve as markers associated with poorer prognosis in sarcomas." (PMID 36153321, 2022). "Further, tumors formed from the low BMP-6-producing osteosarcoma clone (CMT-U353 B, clone 6) were only weakly positive for BMP-6 protein." (PMID 19771160, 2009). "Meanwhile, the levels of TGFB2, p-Smad2, p-Smad3, and BMP-6 showed a reverse trend after the SRI-011381 application, suggesting that PNO1 could influence the progression of osteosarcoma cells via the TGF-β signaling pathway." (PMID 38071381, 2023). "The role of BMP-6 in osteosarcoma development is not well explored." (PMID 36139691, 2022).
renal cell carcinoma (5 papers, 2017 to 2024). "BMP6 has been reported to promote IL-10 specific macrophage M2 polarization in renal cell carcinoma, which coincides with our findings in colorectal carcinoma." (PMID 38970064, 2024). "The initiation and progression of renal cell carcinoma (RCC) is promoted by BMP-6-mediated IL-10 expression, which regulates M2 polarization." (PMID 28915705, 2017). "Similarly, in renal cell carcinoma BMP-6 production supports M2 macrophages and subsequent cancer progression." (PMID 32318332, 2020). "In renal cell carcinoma (RCC), BMP-6 mediates a crosstalk between tumor cells and TAM, too." (PMID 33842333, 2021).